DCDC2C (doublecortin domain containing 2C)
Tractability: No criterion of Open Targets' tractability assessment is met for any kind of drug.
Gene: Protein-coding gene on chromosome 2 (3,703,575 to 3,848,008, forward strand). Ensembl gene ENSG00000214866.
Subcellular location: Cell projection, cilium, flagellum; Cytoplasm
Subcellular location (Human Protein Atlas): End piece
Gene Ontology:
Biological process: intracellular signal transduction
Cellular component: cytoplasm; sperm end piece; sperm flagellum; microtubule; microtubule organizing center; motile cilium; organelle
Genetic constraint (gnomAD): Loss-of-function variants: 44 observed, 37.76 expected, observed/expected ratio (o/e) 1.17, 90% interval 0.91 to 1.5. The upper end of that interval is the gene's LOEUF score, 1.5, which puts it in group 6 of 6, group 1 being the genes least tolerant of losing a copy. Missense variants: 415 observed, 384.1 expected, observed/expected ratio (o/e) 1.08, 90% interval 1 to 1.17. Synonymous variants: 178 observed, 145.01 expected, observed/expected ratio (o/e) 1.23, 90% interval 1.09 to 1.39.
Homologues: Orthologues: chimpanzee DCDC2C (96% identical), macaque DCDC2C (95% identical), dog DCDC2C (76% identical), pig DCDC2C (72% identical), mouse Dcdc2c (71% identical), rabbit DCDC2C (71% identical), rat Dcdc2c (70% identical). Paralogues in human: DCDC2 (33% identical), DCDC2B (31% identical).
Diseases named in the same sentence as DCDC2C in open-access papers:
DCDC2C is named in the same sentence as 1 disease in open-access papers, as found by Europe PMC text mining. Sharing a sentence is not in itself a finding about the gene and the disease. The quoted sentences say what the papers report.
diabetes (1 paper, 2019). "In total, of the top five association signals that were mapped to genes (n = 103) we found five (CDKAL1, DCDC2C, KLF12, LPIN2, TLE1) to be related with diabetes." (PMID 31818369, 2019).